CARM1 (coactivator associated arginine methyltransferase 1)
Diseases named in the same sentence as CARM1 in open-access papers (continued):
Sharing a sentence is not in itself a finding about the gene and the disease.
hepatocellular carcinoma (14 papers, 2020 to 2025). A malignant tumor that arises from hepatocytes. "CARM1 as an Inhibitor of Ferroptosis in Hepatocellular Carcinoma (HCC): A CRISPR-Cas9 library screening revealed that coactivator-associated arginine methyltransferase 1 (CARM1) is an essential inhibitor of ferroptosis in HCC cells." (PMID 40002678, 2025). "This discovery suggests that CARM1‐mediated methylation of GAPDH is a crucial regulatory mechanism in the glucose metabolism of hepatocellular carcinoma." (PMID 39964832, 2025). "In hepatocellular carcinoma, CARM1 acts as a tumor suppressor, sensing changes of glucose in an AMPK-dependent form." (PMID 39715739, 2024). "However, the expression level, clinical significance, biological function, and molecular mechanism of CARM1 in hepatocellular carcinoma (HCC), particularly the downstream genes regulated by CARM1 through histone arginine methylation, remain unclear." (PMID 40016178, 2025). "SKP2 promotes HCC (hepatocellular carcinoma) progression and its autophagy-induced nuclear function via CARM1 and AMPK." (PMID 38020920, 2023). "In hepatocellular carcinoma patients, the R234 site of GAPDH is in a low methylation state, with CARM1 levels positively correlating with the methylation degree at R234." (PMID 39964832, 2025). "In hepatocellular carcinoma (HCC) studies, CARM1 has been found to be a key inhibitor of ferroptosis." (PMID 40143112, 2025). "They focused on CARM1, which methylates GAPDH at R234 and inhibits its catalytic function in hepatocellular carcinoma (HCC)." (PMID 32549751, 2020). "Similarly, in hepatocellular carcinoma, PSMD14-mediated deubiquitination stabilizes CARM1, leading to the transcriptional activation of FERMT1 and subsequent promotion of proliferation and metastasis." (PMID 41488674, 2025).
gastric cancer (12 papers, 2022 to 2025). A primary or metastatic malignant neoplasm involving the stomach. "The NRF2–Coactivator associated arginine methyltransferase 1 (CARM1) axis epigenetically regulates PPP enzymes in gastric cancer, whereas MYC-dependent NRF2 activation drives similar programs in head and neck tumors." (PMID 41470226, 2025). "Here, we demonstrate that coactivator-associated arginine methyltransferase 1 (CARM1) is frequently overexpressed in gastric cancer and predicts poor prognosis of patients with this cancer." (PMID 39266534, 2024). "CARM1-mediated transcriptional activation of the NOTCH2 signaling pathway is linked to NOTCH2 methylation in gastric cancer progression." (PMID 37536629, 2023). "Further, overexpression of a specific leucine-rich repeat (in FLII)-interacting protein 2 (LRRFIP2) splice variant that directly interacts with CARM1 and activates it, also contributes to the metastasis of gastric cancer cells." (PMID 37536629, 2023). "Overexpression of LRRFIP2 variant 3 contributed to the metastasis of gastric cancer cells by modulating the histone methylation activity of coactivator-associated arginine methyltransferase 1 (CARM1)." (PMID 36307405, 2022). "For gastric cancer patients with lymph node metastasis, highly expressed CARM1 is associated with poor OS, FP and PPS prognosis." (PMID 35033016, 2022). "In addition, the study found that coactivator associated arginine methyltransferase 1 Gene(CARM1) is overexpressed in gastric cancer." (PMID 40977700, 2025). "ACTR knockdown reduced the asymmetric dimethylation of histone H3R17 in gastric cancer cells, suggesting that transcriptional regulation of target genes by CARM1 through histone methylation might be largely associated with ACTR expression." (PMID 36307405, 2022). "Our previous studies have shown that PRMT1 and PRMT4/CARM1 promote gastric cancer proliferation and metastasis, underscoring the significance of NUSAP1 interactions with PRMT1 and PRMT5." (PMID 40393971, 2025). "LRRFIP2 expression is higher in high ESRP1-expressing cell lines, while LRRFIP variant 3 is higher in low ESRP1-expressing cell lines, determining gastric cancer cell metastasis via differential protein interaction with methyltransferase CARM1." (PMID 40046628, 2025). "To investigate the clinical relevance of CARM1 in gastric cancer, we examined the expression patterns of CARM1 in human gastric cancer tissues." (PMID 39266534, 2024). "The PPP-enhanced activity in a CARM1-dependent manner produces intermediate metabolites for ROS scavenging and nucleic acids, thereby facilitating the survival and growth of gastric cancer cells under metabolic stress." (PMID 39266534, 2024). "In our study, we demonstrated that the upregulation of CARM1 in gastric cancer promotes glucose influx toward the PPP under metabolic stress by regulating the gatekeeper enzyme G6PD." (PMID 39266534, 2024). "To facilitate a more comprehensive assessment of the impact of CARM1-regulated PPP regulation on the malignant behaviors of gastric cancer cells, we employed relatively high concentrations of 6-AN to ensure maximum inhibitory effects on the PPP." (PMID 39266534, 2024). "Collectively, this study reveals a significant role of CARM1 in regulating the tumor metabolic switch and identifies CARM1 as a potential therapeutic target for gastric cancer treatment." (PMID 39266534, 2024). "Targeted metabolomics analysis showed that knockdown of CARM1 in gastric cancer cells under low glucose conditions resulted in significant changes of various metabolites." (PMID 39266534, 2024). "We discovered that CARM1 can modulate the glucose metabolic pathway in gastric cancer cells by enhancing the PPP to confront the stress of nutrient deprivation, consequently facilitating cell survival and proliferation." (PMID 39266534, 2024).
gastric cancer (continued). "Collectively, the results indicate that the upregulation of CARM1 induced by glucose starvation supports cell growth and survival in gastric cancer cells through its positive regulation of the PPP." (PMID 39266534, 2024). "Glucose deprivation significantly increased the intracellular ROS levels in MGC-803 and AGS cells, and CARM1 knockdown led to a further increase of ROS levels in gastric cancer cells, indicating the involvement of CARM1 in the regulation of cellular ROS." (PMID 39266534, 2024). "Similar to CARM1 knockdown, 6-AN treatment effectively inhibited the proliferation of gastric cancer cells under low glucose conditions and was accompanied by substantial decreases in the levels of NADPH." (PMID 39266534, 2024). "We observed that knockdown of CARM1 decreased the asymmetric dimethylation of H3R17 in gastric cancer cells, as expected." (PMID 36307405, 2022). "In addition, although detailed studies and further validation are needed to assess their clinical significance, we propose that LRRFIP2 variants (2 or 3) may serve as potential biomarkers for gastric cancer liver metastasis and as therapeutic biomarkers for CARM1 inhibitors." (PMID 36307405, 2022). "The mRNA expression of CARM1 was also significantly increased in gastric cancer tissues compared to normal tissues." (PMID 36307405, 2022). "The upregulation of CARM1 induced by glucose starvation suggests that it may play an important role in gastric cancer cells in response to low glucose stress." (PMID 39266534, 2024). "Given the observed function of CARM1 in cell growth and its effect on PPP activation, we speculated that gastric cancer cell proliferation and survival under low glucose conditions would rely on CARM1-mediated PPP activity." (PMID 39266534, 2024). "Moreover, statistical analysis revealed a strong correlation between NRF2 and CARM1 at the protein level in gastric cancer tissues." (PMID 39266534, 2024). "High CARM1 expression has been correlated with poor prognosis in gastric cancer." (PMID 37536629, 2023). "Given that CARM1 is an arginine methyltransferase, it would be of interest to determine whether the methyltransferase activity of CARM1 is critical for the transcriptional regulation of SERPINE1 in gastric cancer cells." (PMID 36307405, 2022). "Considering that CARM1 expression is critical for SERPINE1 expression, we also examined whether CARM1 actually affected the migration and invasion of gastric cancer cells." (PMID 36307405, 2022). "For example, a low-glucose environment around gastric cancer cells can upregulate NRF2 expression, which promotes protein arginine methyltransferase 4 (PRMT4, also named CARM1) transcription." (PMID 40227215, 2025). "Further research indicated that inhibition of CARM1 enzymatic activity leads to a decrease in SERPINE1 expression and subsequently eliminates the invasive potential of gastric cancer cells." (PMID 39964832, 2025). "Immunoblotting of gastric cancer sample tissues and their adjacent normal tissues demonstrated that CARM1 and NRF2 protein levels were significantly higher in gastric cancer tissue relative to surrounding normal tissue." (PMID 39266534, 2024). "By inhibiting CARM1, the invasiveness of LRRFIP2-overexpressing gastric cancer cells can likely be repressed." (PMID 37536629, 2023). "Collectively, these results consistently indicate that the inhibition of CARM1 enzymatic activity results in the repression of SERPINE1 expression and subsequently abrogates the invasive potential of gastric cancer cells." (PMID 36307405, 2022). "As revealed by immunohistochemistry (IHC) staining, the expression level of CARM1 was significantly higher in gastric cancer tissues compared with adjacent noncancerous tissues." (PMID 39266534, 2024). "Furthermore, CARM1 enhances the binding between N2ICD and MAML1 by methylating the Notch2 intracellular domain (N2ICD), thereby promoting the proliferation and tumorigenesis of gastric cancer cells." (PMID 39964832, 2025).
gastric cancer (continued). "Notably, the inhibitory effect of 6-AN on the proliferation of gastric cancer cells in CARM1 knockdown cells showed no further reduction." (PMID 39266534, 2024). "However, the effect of CARM1 on gastric cancer (GC) has not been studied." (PMID 35246137, 2022).
liver cancer (12 papers, 2019 to 2025). An epithelial or non-epithelial malignant neoplasm that arises from the liver. "In particular, our results suggest that miR-933 enhances the expression of PKM2 and the interaction between PKM2 and CARM1 in liver cancer." (PMID 38434754, 2024). "Current data showed that there were AMPK-ERK/CARM1 autophagic signaling pathways during the formation of liver cancer." (PMID 31799198, 2019). "However, another study revealed that glucose starvation-induced CARM1 expression induces GAPDH hypermethylation to suppress glycolysis in liver cancer cells, indicating a tumor-suppressive role of CARM1." (PMID 40016178, 2025). "Next, we analyzed whether ARAF knockdown influenced the carcinogenic functions of CARM1 in liver cancer." (PMID 39415943, 2025). "Collectively, these observations suggest that miR-933 could enhance the expression of PKM2 via CREB1 and the interaction between PKM2 and CARM1 in human liver cancer." (PMID 38434754, 2024). "To further investigate how miR-933 affects the expression of PKM2 and the interaction between PKM2 and CARM1 in human liver cancer, we explored whether several important genes were involved in the regulation of this function." (PMID 38434754, 2024). "We hypothesize that the AMPK-ERK/CARM1 signaling pathways play important roles in the progression of liver cancer." (PMID 31799198, 2019). "Moreover, it suggests that CARM1 may be a potential therapeutic target for liver cancer, which is of great significance for early diagnosis and optimization of treatment strategies for liver cancer." (PMID 39415943, 2025). "In this study, it is revealed that CARM1 affects the epigenetic modification, transcriptome, and proteome to regulate the expression of related genes in liver cancer, thus regulating cell proliferation, cell metabolism, cell cycle, and other biological processes in liver cancer cells." (PMID 39415943, 2025). "In addition, CARM1-mediated GAPDH methylation inhibits glycolysis in liver cancer cells." (PMID 34737767, 2021). "Given miR-933's role in enhancing the expression of PKM2 and the interaction between PKM2 and CARM1, we considered whether miR-933 resulted in carcinogenic functions dependent on PKM2 in liver cancer." (PMID 38434754, 2024). "CARM1 was previously reported to suppress the glycolysis in liver cancer cells by mediating arginine 234 (R234) methylation of GAPDH, thus inhibiting the proliferation of liver cancer cells." (PMID 39567506, 2024).
breast tumors (11 papers, 2008 to 2025). "The pyruvate kinase M2 isoform, a key glycolytic enzyme, undergoes methylation by coactivator-associated arginine methyltransferase 1 (CARM1), which results in the activation of aerobic glycolysis, promoting the development of breast tumors." (PMID 40548063, 2025). "We compared the expression of CARM1 in a cohort of clinical breast tumor samples (n=1,102) to that of normal breast tissues (n=113) and found that its expression was significantly higher in tumors than normal tissues." (PMID 32206101, 2020). "By analyzing ∼300 ERα-positive human breast tumor biopsy samples, we found that the expression level of CARM1 positively correlated with ERα level in low-grade tumors." (PMID 23723242, 2013). "Furthermore, the study also found that in human breast tumours, CARM1 expression is positively correlated with ERα levels in ER‐positive tumours but negatively correlated with tumour grade, indicating that CARM1 is an important epigenetic target in ER‐positive breast cancer." (PMID 39964832, 2025). "Targeting CARM1 with EZM2302, a CARM1-specific inhibitor, significantly inhibits CARM1-mediated GATAD2A methylation, cell cycle gene transcription, cell cycle progression, and breast tumor growth." (PMID 38676947, 2024). "Furthermore, the recruitment of Carm1 is dependent on the SRC-3 coactivator, which is overexpressed in aggressive breast tumors concomitantly with a Carm1 overexpression." (PMID 27556302, 2016). "The ESR1 gene is shared among 3 pathways: "PELP1 Modulation of Estrogen Receptor Activity pathway", "CARM1 and Regulation of the Estrogen Receptor pathway", and "Downregulated of MTA 3 in ER negative Breast Tumors pathway"." (PMID 18254968, 2008).
acute myeloid leukemia (9 papers, 2022 to 2026). Acute myeloid leukemia (AML) is a group of neoplasms arising from precursor cells committed to the myeloid cell-line differentiation. "The enzyme co-activator-associated arginine methyltransferase 1 (CARM1) is highly expressed in a variety of cancers, such as Hodgkin's lymphoma and acute myeloid leukemia, and CARM1 is closely associated with tumor cell proliferation." (PMID 37477799, 2023). "Thus, Carm1-deficient mice are resistant to MLL-AF9-induced acute myeloid leukemia, probably because a critical target protein cannot be methylated by the enzyme." (PMID 37365888, 2023). "The presence of the JAK2-V617F mutant kinase renders acute myeloid leukemia (AML) cells less sensitive to CARM1 inhibition, and we show that the dual targeting of JAK2 and CARM1 is more effective than monotherapy in AML cells expressing phospho-CARM1." (PMID 38649367, 2024). "There are two studies that provide evidence for cross-talk between CARM1 and RUNX1 (also called acute myeloid leukemia [AML] 1), a transcription factor that regulates genes with important functions in normal and malignant hematopoiesis." (PMID 37536629, 2023). "CARM1 was reported to have pairwise synergistic interaction with other histone methyltransferases, like disruptor of telomeric silencing 1-like (DOT1L), jointly coordinating K562 (acute myeloid leukemia [AML]) cell survival." (PMID 40123976, 2025).
non-small cell lung carcinoma (8 papers, 2020 to 2026). A group of at least three distinct histological types of lung cancer, including non-small cell squamous cell carcinoma, adenocarcinoma, and large cell carcinoma. "In non-small cell carcinoma, GA inhibits the activation of the epidermal growth factor receptor (EGFR) and prevents coactivator-associated arginine methyltransferase 1 (CARM1) from binding to proline, glutamate, and leucine-rich protein 1 (PELP1)." (PMID 40786042, 2025). "In non-small cell lung cancer, lncRNA PVT1 induced radioresistance through miR-424-5p/CARM1, while CARM1 (coactivator associated arginine methyltransferase 1) is involved in DNA packaging, transcription regulation, pre-mRNA splicing, and mRNA stability." (PMID 35600868, 2022). "Pre-clinical testing for PRMT4/CARM1 has included the use of another inhibitor, TBBD, in non-small cell lung carcinoma cell lines." (PMID 33440687, 2021).
colon cancer (7 papers, 2010 to 2024). "Additionally, the analysis data obtained from cBioPortal tool shows that the mutation of CARM1 gene is related to the poor prognosis of colon cancer, which has been proved to be highly expressed CARM1 protein by CPTAC analysis tool." (PMID 35033016, 2022). "CARM1 is often overexpressed in several major cancer types, including ovarian, breast and colon cancers." (PMID 39266534, 2024). "Subsequently, IHC staining of a tissue chip containing 78 clinical specimens of malignant colon tumors was used to evaluate the survival curve, and patients with high CARM1 levels demonstrated significantly shorter overall survival." (PMID 37946697, 2023). "Since the tissue microarray showed that almost 70% of the colon cancers overexpressed CARM1, further studies were performed to confirm the expression of CARM1 in the colon cancers of surgically acquired specimens from the Indiana University Tissue Bank." (PMID 20462455, 2010). "CARM1 was highly expressed in some of the selected colon tumors while its expression was weak in the normal mucosal cells." (PMID 20462455, 2010). "Furthermore, the results of the CPTAC dataset indicate higher expression of CARM1 protein in the primary tissues of KIRC and colon cancer than in normal tissues, and increase from grade I to grade II in KIRC patients." (PMID 35033016, 2022).